INS (insulin)
Diseases named in the same sentence as INS in open-access papers (continued):
Sharing a sentence is not in itself a finding about the gene and the disease.
colorectal cancer (continued). "Butyrate is an essential energy source for the gut mucosa; helps to protect against colorectal cancer; and has several physiological effects related to inflammation, the immune system, oxidative stress, gut barrier function, satiety, and insulin sensitivity." (PMID 38930808, 2024). "Of those cancers that showed decreased risk of GLP-1RAs compared with insulin, risk reduction was also noted for GLP-1RAs relative to metformin for colorectal cancer, gallbladder, and meningiomas, although these findings were not statistically significant." (PMID 38967919, 2024). "In summary, anatomical factors, chronic inflammatory response, insulin resistance, and microcirculation disturbance jointly contributed to infectious outcomes following colorectal cancer resection." (PMID 37653410, 2023). "Leptin and insulin upregulate miR-4443 in colorectal cancer and decrease the invasiveness of colon cancer cells." (PMID 36964242, 2023). "FGF19 can promote the occurrence of colorectal cancer by regulating metabolic biological functions, such as bile acid biosynthesis and insulin resistance." (PMID 36751636, 2023). "Here, we quantified the roles of leptin and C‐reactive protein, fasting insulin, and estradiol in explaining the effect of high BMI on estrogen receptor‐positive breast, endometrial, and colorectal cancers in postmenopausal women." (PMID 35048536, 2022). "For colorectal cancer, there was evidence for mediating effect through fasting insulin, while the point estimates for indirect effects through leptin and CRP, and estradiol were essentially null." (PMID 35048536, 2022). "High insulin levels will not only accelerate the progression of colorectal cancer but also affect its treatment and prognosis." (PMID 34485124, 2021). "In conclusion, our in vitro data suggest that the stimulating effects of glucose, IGFs and insulin on proliferation differ between colorectal cancer cells from early and late Dukes’ stages." (PMID 34290976, 2021). "The insulin/IGF system was implicated in the development of drug resistance to epidermal growth factor receptor‐targeted agents and chemotherapeutic drugs in colorectal cancer." (PMID 34528373, 2021). "For example, a recent study found that prescribing 150 min/week of aerobic exercise for 6 months to colorectal cancer survivors lowered serum insulin concentrations." (PMID 33801684, 2021). "In conclusion, our data suggest that there is a dissociation between the effects of glucose, IGF-I, IGF-II and insulin on cell proliferation between early and late stage colorectal cancer cells." (PMID 34290976, 2021). "The probable mechanisms of colorectal cancer prevention through physical activity are related to insulin levels, inflammation, myokine levels, and immune responses." (PMID 34683079, 2021). "In colorectal cancer, down-regulation of MTMR7 was associated with a malignant phenotype by reducing the level of phosphoinositide and the activity of insulin-mediated AKT-ERK1/2 signaling." (PMID 32701143, 2020). "Adiponectin as an insulin sensitizer and a negative regulator of angiogenesis mainly secreted from visceral adipose tissue, has been shown to inhibit colorectal cancer in animal experiments and has been related to colorectal cancer risk in clinical trials." (PMID 32466596, 2020). "In this research, we focused the relationship between insulin and colon cancer, and we found insulin-triggered cell proliferation and metastatic effects on colorectal cancer cells are mediated by ACAT1." (PMID 29793481, 2018). "Insulin-triggered cell proliferation and metastatic effects on colorectal cancer cells are mediated by ACAT1." (PMID 29793481, 2018). "Metabolic syndrome, elevated levels of insulin and insulin-like growth factors which inhibits apoptosis and modulates cell proliferation are suggested to play a role in the aetiology of colorectal cancer." (PMID 29080978, 2018).
colorectal cancer (continued). "AHSG is a multifunctional glycoprotein involved in numerous normal and pathological processes such as brain development, bone metabolism regulation, insulin resistance, migration and invasion in human colorectal cancer." (PMID 29719494, 2018). "This in vitro study aims to determine the anticancer effects of 2DG and the effects of insulin on colorectal cancer cell lines." (PMID 26939025, 2016). "This is consistent with the evidence from a meta-analysis − based on seven case–control studies and five cohort studies published before 2014 − which reported an overall RR of colorectal cancer of 1.69 (95% CI 1.25–2.27) for insulin users." (PMID 27766252, 2016). "Understanding the glucose metabolism and the function of insulin in colorectal cancer cells will promote the development of some novel approaches for its prevention and treatment." (PMID 26939025, 2016). "Recent study demonstrated that one of the CRNDE transcripts, gVC-In4, contains a highly-conserved sequence within intron 4 and promotes metabolic changes through insulin/IGF signaling in colorectal cancer cells." (PMID 27637083, 2016). "Among antidiabetic medications, it indicates a favorable effect for metformin use and a detrimental effect for insulin use, suggesting a need for enhanced screening measures for colorectal cancer in insulin-treated patients." (PMID 27766252, 2016). "Participation in a 12 week home exercise program, developed for colorectal cancer survivors showed a reduction in insulin levels." (PMID 27781180, 2016). "Insulin injection has also been shown to stimulate the growth of colorectal cancer precursors in animal models." (PMID 27766252, 2016). "By contrast, insulin has been found to decrease the toxic effects of 5-FU in HT29 colorectal cancer cells." (PMID 24396438, 2014). "The insulin/insulin-like growth factor pathway is involved in breast and colorectal cancer (CRC) development." (PMID 23877285, 2013). "First, the earlier study was a case-cohort study conducted in the WHI OS and had a larger sample size (438 colorectal cancer cases) and measured a number of hormones, including insulin, IGF-1, and estradiol." (PMID 22127286, 2012). "In a previous study conducted within the Women's Health Initiative Observational Study, we showed that serum insulin, waist circumference, and free IGF-1 were each positively associated with colorectal cancer incidence in multivariate models." (PMID 22127286, 2012). "It is instructive to note that among these pathways, some have been proved to be relevant to colorectal cancer including Wnt signaling pathway, cell cycle, colorectal cancer and insulin signaling pathway." (PMID 22496748, 2012). "Previous studies have demonstrated that insulin signaling has an important role in colorectal cancer progression." (PMID 21172019, 2010). "In conclusion, our results provide no clear support for an overall protective effect of magnesium on colorectal cancer in men or women, but are compatible with an impact in the subgroup of overweight subjects, possibly through reduced insulin resistance." (PMID 17285123, 2007). "In the Netherlands Cohort Study (NLCS), we investigated colorectal cancer in both sexes in relation to magnesium intake, particularly in overweight subjects, given the suggested beneficial effects of magnesium on insulin resistance." (PMID 17285123, 2007). "In one of the patients in particular, when luseogliflozin was discontinued and switched to insulin treatment before colorectal cancer surgery, ascites accumulation was observed within two weeks, which subsequently decreased rapidly when luseogliflozin was restarted." (PMID 40704640, 2025). "Elevated C-peptide levels, a marker of insulin secretion, and an increased colorectal cancer risk." (PMID 40175445, 2025).
colorectal cancer (continued). "High insulin levels stimulate the production of IGF-1 by liver cells after insulin binds to its receptor, whereas IGF-1 can also bind to insulin-like growth factor binding protein 3 (IGFBP-3), which is associated with a greater risk of colorectal cancer." (PMID 40457130, 2025). "BPA along with phthalates mimics hormones, such as estrogen, which can interfere with insulin signaling processes as well as adipogenesis; they may also encourage colorectal cancer cell proliferation through activation of estrogen receptor‐β." (PMID 41498107, 2025). "Although the exact mechanism remains unclear, studies also suggest a connection between gut microbiota and insulin sensitivity, inflammatory bowel disease, and colorectal cancer." (PMID 41156555, 2025). "Insulin or sulfonylurea use was not linked to a changed likelihood of developing colorectal cancer [RR 1.44; 95% CI (1.09–2.0)]." (PMID 40572709, 2025). "Physical activity plays a crucial role in modulating insulin sensitivity, significantly influencing the prevention and progression of various types of cancer, particularly those of the gastrointestinal tract, such as colorectal cancer." (PMID 41178954, 2025). "Insulin-mediated pathways plausibly explain the pathogenesis of colorectal cancer (CRC)." (PMID 39103728, 2024). "Therefore, this study aimed to evaluate the efficacy and safety of intranasal insulin on POCD in elderly patients after laparoscopic radical resection of colorectal cancer." (PMID 38915348, 2024). "However, there is limited clinical evidence of intranasal insulin preventing POCD in elderly patients after laparoscopic radical resection of colorectal cancer." (PMID 38915348, 2024). "Medical analysis suggests that estrogen may affect the growth rate of colorectal cancer, and insulin may also have a direct tumor-promoting effect." (PMID 36836694, 2023). "Raised insulin levels can contribute to increased circulating levels of insulin-like growth factor I (IGF-I), which promotes cell proliferation and inhibits apoptosis and is positively associated with the risk of colorectal cancer." (PMID 36684119, 2022). "However, insulin use can have unintended effects, with reports of increased cardiovascular events and increased colorectal cancer in patients on insulin therapy." (PMID 35227220, 2022). "GAL and its receptor GalR1 might have novel potential for overcoming chemotherapy resistance though mitogen-activated protein kinase signaling and the insulin signaling pathway in colorectal cancer." (PMID 35751103, 2022). "In contrast, a longitudinal study with a median follow-up period of 11.9 years demonstrated that serum insulin was not related to the risk of colorectal cancer in postmenopausal women." (PMID 35530326, 2022). "Several studies have also identified a link between markers of heightened insulin levels (eg, C‐peptide) and colorectal cancer risk, but without finding any evidence of heterogeneity." (PMID 35383926, 2022). "For colorectal cancer, analyses in the EPIC‐Italy and WHI studies found positive association for circulating PAI‐1,9, 13 although the WHI positive association were attenuated toward the null after adjusting for circulating insulin concentration." (PMID 33038280, 2021). "In the present study, we studied in vitro in human colorectal cancer cells originating from four Dukes’ stages of colorectal cancer the effects of glucose, insulin and IGFs on proliferation, migration, cell cycle progression and gene expression of the IGF system." (PMID 34290976, 2021). "Therefore, in the present study we investigated the potential effects of glucose, insulin and IGFs on proliferation, migration, cell cycle progression and gene expression in colorectal cancer cells originating from four different Dukes’ stages (A, B, C and D)." (PMID 34290976, 2021).
colorectal cancer (continued). "The possible mechanisms explaining the increased colorectal cancer risk might be a direct effect of IGF1 on cell growth or an indirect effect, such as insulin resistance and raised insulin levels." (PMID 34858769, 2021). "Current study findings therefore suggest that the direct effect of the diet on insulin may be more important than the effect of diet on glucose for colorectal cancer prognosis." (PMID 32854644, 2020). "It is important to understand that the insulin index, which was used in most previous studies of dietary insulinemic potential and colorectal cancer survival, is conceptually and technically different from the EDIH, and essentially uncorrelated (Spearman r = − 0.03)." (PMID 32854644, 2020). "Our data suggest that SFRP2 methylation (and loss expression of SFRP2) may be a potential candidate in the insulin sensitivity and colorectal cancer axis." (PMID 32517740, 2020). "Additionally, the downregulation of the insulin and insulin-like growth factor-1 receptors was correlated to a greater decrease in the proliferation and migration of chemoresistant colorectal cancer cells." (PMID 30987250, 2019). "Interestingly, we found that other metabolic and cancer pathways were also enriched, including the insulin signaling, colorectal cancer, and mitogen-activated protein kinase (MAPK) signaling pathways." (PMID 31484384, 2019). "Although a meta-analysis showed that association between insulin treatment and increased risk of colorectal cancer is not significant." (PMID 30413050, 2018). "To further determine whether inhibition of the Akt/mTOR pathway is involved in TCO–induced autophagy, we activated the Akt/mTOR pathway by combinatorial treatment with insulin (Akt activator) in colorectal cancer cells." (PMID 28881770, 2017). "Patients with concomitant colorectal cancer and type 2 DM who may also use insulin are facing the potential threat that insulin may promote cancer progression." (PMID 26939025, 2016). "The strategy of combining 2DG and insulin proved to be promising against colorectal cancer and might be helpful in the treatment of other malignancies." (PMID 26939025, 2016). "This review will discuss the role of the insulin/IGF system in colorectal cancer (CRC)." (PMID 26528439, 2015). "Appropriate use of ADTs with metformin, α-glucosidase inhibitor and long-acting insulin might have a protective effect against the development of liver and colorectal cancer." (PMID 25978841, 2015). "Based on these observations, we hypothesized that chronic exogenous insulin therapy among patients with T2DM may promote colorectal cancer development." (PMID 24885616, 2014). "Furthermore, in an animal model, exogenous insulin injection stimulates the growth of colorectal cancer precursors." (PMID 24885616, 2014). "We have previously shown that elevated insulin may contribute to the development of adenomas, the precursors to most colorectal cancer." (PMID 24885616, 2014). "Insulin, insulin-like growth factor 1 and 2 (IGF-1 and IGF-2) and IGF binding protein (IGFBP) are involved in cell growth and survival and are thought to be implicated in colorectal cancer (CRC)." (PMID 23877285, 2013). "Compared with non-glargine insulin, Insulin glargine use was associated with lower odds of gastrointestinal cancer, colorectal cancer, hepatobiliary cancer and bladder cancer." (PMID 23284776, 2012). "Alternatively, IGF and insulin may be factors that accelerate colorectal cancer growth and inhibit apoptosis and high 25(OH)D may be a factor that helps reduce proliferation and induce apoptosis through complementary pathways or mechanisms." (PMID 22216097, 2011). "In addition, IGF2 is known to be overexpressed in cancer and specifically, insulin signaling has been demonstrated to play a role in colorectal cancer." (PMID 21172019, 2010).
colorectal cancer (continued). "Intranasal insulin may decrease the risk of POCD and inhibit the elevated serum IL-6, TNF-α, and S100β levels in elderly patients after laparoscopic radical resection of colorectal cancer, which proves that intranasal insulin may be a promising therapeutic option for POCD." (PMID 38915348, 2024). "Although further studies are warranted, dysregulated insulin pathways, rather than a consequence of impaired glucose metabolism, might have a higher chance of increasing colorectal cancer risk." (PMID 37120602, 2023). "For instance, insulin therapy has been associated with increased risk of newly developed colorectal cancer, however we could not account for this in the model." (PMID 32132977, 2020). "Furthermore, we recently reported that 12 week of a home-based exercise program, the same exercise protocol used in the current study, not only increased physical activity and improved physical function, but also significantly reduced circulating insulin levels in colorectal cancer survivors." (PMID 29698416, 2018). "Moreover, it indicates a negative association between colorectal cancer and metformin use and a positive association for insulin use." (PMID 27766252, 2016). "Diabetic patients using insulin had an increased risk of colorectal cancer as compared with those not using it (OR 2.20, 95% CI 1.12–4.33); the OR increased with increasing duration of insulin use and was 8.18 (95% CI 2.06–32.50) for ≥10 years of use (p-value for trend 0.002)." (PMID 27766252, 2016). "Other lifestyle risk factors for colorectal cancer, such as increased caloric intake, being overweight, and having a sedentary lifestyle, have demonstrated higher levels of IGF-1 via increased insulin production and subsequent inhibition of IGF-binding protein synthesis." (PMID 27598322, 2016). "However, a diet high in foods that increased postprandial insulin levels did not increase the risk of colorectal cancer in a large prospective epidemiological study." (PMID 26347815, 2015). "When all four studies were analyzed, the summary RRs were 1.61 (95% CI = 1.18–1.35) in a random-effects model for individuals with insulin therapy, compared with individuals without insulin therapy, which suggests a statistically significant association between insulin use and colorectal cancer." (PMID 24175949, 2013). "In addition, given that the potential effect of magnesium on colorectal cancer might be mediated through improving insulin sensitivity, we also tested whether plasma levels of C-peptide, a validated marker for insulin secretion, vary by magnesium intake." (PMID 22415230, 2012). "Clinical trials confirm these associations: in a phase II RCT, 6 months of moderate aerobic exercise reduced fasting insulin and HOMA-IR in colorectal cancer survivors, with greater benefits in those with higher exercise volumes (up to −20 pmol/L)." (PMID 41178954, 2025). "For the “tumor” variable in the colorectal cancer dataset GSE199057, the Reactome pathways “acetylcholine regulates insulin secretion” and “fatty acids bound to GPR40 (FFAR1) regulate insulin secretion” were both significantly enriched." (PMID 40050559, 2025). "IRS1, an insulin signaling pathway gene, expressed stronger immunostaining in colon adenomas from FAP and in colorectal cancers and is suggested to play a role in colon tumor development." (PMID 38609520, 2024). "Recent studies have implicated DPA in the improvement of several metabolic disease markers, including insulin sensitivity, and DPA has been shown to display a greater anti-inflammatory effect than EPA or DHA in a model of colorectal cancer." (PMID 35498414, 2022). "This is supported by data from a 12-week home-exercise intervention consisting of aerobic and bodyweight strength exercises that decreased plasma insulin-concentrations and improved the HOMA-IR index in colorectal cancer survivors." (PMID 33801684, 2021).